IDNK (IDNK gluconokinase)
Description:
[Isoform 1]: Phosphorylates gluconate to 6-phosphogluconate.
Synonyms: C9orf103; bA522I20.2; hGntK
Tractability: PROTAC: its protein half-life has been measured.
Gene: Protein-coding gene on chromosome 9 (83,623,049 to 83,644,137, forward strand). Ensembl gene ENSG00000148057.
Subcellular location (Human Protein Atlas): Cytosol; Mitochondria
Gene Ontology:
Molecular function: gluconokinase activity; kinase activity
Biological process: carbohydrate metabolic process
Genetic constraint (gnomAD): Loss-of-function variants: 13 observed, 14.96 expected, observed/expected ratio (o/e) 0.87, 90% interval 0.56 to 1.38. The upper end of that interval is the gene's LOEUF score, 1.38, which puts it in group 5 of 6, group 1 being the genes least tolerant of losing a copy. Missense variants: 204 observed, 226.13 expected, observed/expected ratio (o/e) 0.9, 90% interval 0.8 to 1.01. Synonymous variants: 89 observed, 91.21 expected, observed/expected ratio (o/e) 0.98, 90% interval 0.82 to 1.16.
Homologues: Orthologues: macaque IDNK (84% identical), pig IDNK (82% identical), dog IDNK (79% identical), mouse Idnk (73% identical), rat Idnk (68% identical), tropical clawed frog idnk (52% identical), Caenorhabditis elegans ZK938.3 (18% identical).
Diseases named in the same sentence as IDNK in open-access papers:
IDNK is named in the same sentence as 2 diseases in open-access papers, as found by Europe PMC text mining. Sharing a sentence is not in itself a finding about the gene and the disease. The quoted sentences say what the papers report.
tumor (2 papers, 2021 to 2022). "However, L-NMMA, SC, or both compounds did not affect idNK activity towards K562 tumor cells or the expression of lysosomal-associated membrane protein-1 (LAMP-1; CD107a) in our research." (PMID 34768607, 2021).
IDNK also shares sentences with these, for which no sentence is quoted: depression (1 paper).